INS (insulin)
Diseases named in the same sentence as INS in open-access papers (continued):
Sharing a sentence is not in itself a finding about the gene and the disease.
diabetes (continued). "In recent years, PTP1B has been the center of focus because of its ability to attenuate the insulin signaling pathway and is currently considered a therapeutic target against diabetes." (PMID 36875821, 2022). "The animals were recorded with signs of metabolic syndrome and type 2 diabetes mellitus by recording their body weights, glucose and insulin levels, and the calculating HOMA-IRs." (PMID 36555360, 2022). "The two major types of diabetes, i.e., type 1 and 2, are mainly different in terms of insulin level and availability within the body." (PMID 35630740, 2022). "It is concerning as prior research has confirmed that ambulatory persons with diabetes frequently self-administer insulin incorrectly." (PMID 36611495, 2022). "In the case of diabetes treatment, a caveat is that metformin increases insulin sensitivity whereas Klotho has the opposite effect." (PMID 35903083, 2022). "Patients had a mean HbA1c of 7.4% (95% CI, 7.4%-7.5%), 31.0% (29.4%-32.3%) were using insulin, 77.6% (95% CI, 76.3%-78.8%) were using an oral diabetes medication, and the majority had moderate T2D (55.8%; 95% CI, 54.5%-57.2%)." (PMID 35157054, 2022). "Type 2 diabetes mellitus (T2DM) is caused by insulin resistance and the insulin production and secretion decline of β-cells." (PMID 35830425, 2022). "These associations remained significant even after adjustment for each factor such as sex, HbA1c, body weight-adjusted total daily dose of insulin, and the duration of diabetes." (PMID 35216490, 2022). "The STAR 3 randomized clinical trial compared the metabolic control of diabetes in patients treated with a sensor‐augmented personal insulin pump and the metabolic control of patients using multiple insulin pen injections with self‐measured blood glucose." (PMID 35620854, 2022). "Given the positive effects of ALA on insulin sensitivity and the protective effects on damaged beta-cells, we would expect some therapeutic efficacy in the management of diabetes." (PMID 36615676, 2022). "A study from the Republic of Rwanda reported a low knowledge level among nurses in terms of diabetes education, specifically on diet, complications, insulin use and impact of stress." (PMID 36675718, 2022). "Inhibition of circLRP6 and circ_0054633, which are upregulated in diabetes, prevents β-cell apoptosis and restores insulin secretion; they also act as molecular sponges for miR-409-3p and miR-9-5p, respectively, in this process." (PMID 36147580, 2022). "Koebner phenomenon is an uncommon skin-related complication of subcutaneous insulin injection in patients with diabetes mellitus." (PMID 37908249, 2022). "Canine mesenchymal stem cells (cMSCs) have potential applications for regenerative therapy, including the generation of insulin-producing cells (IPCs) for studying and treating diabetes." (PMID 35650303, 2022). "Severe hypoglycemia (below 35 mg/dL) appears most often in diabetes patients who continuously inject insulin." (PMID 35203316, 2022). "The mechanisms of T1DM begin well before full diabetes, as T-cells attack insulin-producing β-cells." (PMID 35324794, 2022). "While being treated inpatient for the foot ulcers, the patient repeatedly refused to receive standard hospital diabetes management of insulin injections." (PMID 35251838, 2022). "The objective of our study was to characterize national trends in glycemic control and severe hyperglycemia among patients with diagnosed diabetes using insulin." (PMID 36538330, 2022). "Age, weight, primary care giver, insulin dose, duration of diabetes, adherence, and carbohydrate counting, including history of comorbidity were determinant factors." (PMID 36153485, 2022). "The long-lasting blood-glucose-lowering effect of IR-A62 that was identified in vivo suggests that IR-A62 has potential as an addition to or a substitute for long-acting insulin in the treatment of diabetes." (PMID 35478209, 2022).
diabetes (continued). "Most participants were married, had diabetes for more than 10 years, and used insulin once or twice a day." (PMID 36568796, 2022). "Transplantation of cells that can release insulin have been reported as an alternate method to islet transfer for curing diabetes; however, the main difficulty facing the quality of the pancreatic cells is the deficiency of oxygen." (PMID 36248064, 2022). "Overall, less than 30% of patients with diabetes using insulin had an HbA1c level less than 7%, while approximately 15% had an HbA1c level greater than 10%." (PMID 36538330, 2022). "Failure to secrete enough insulin by beta cells is a pathological feature of type 2 diabetes mellitus (T2DM)." (PMID 36139075, 2022). "Diabetes mellitus is a group of related metabolic disorders characterized by hyperglycemia ensuing from defects in insulin production, insulin action, or both." (PMID 35799740, 2022). "Diabetes patients are often discouraged from being involved in social events because of their dietary restrictions and insulin administration." (PMID 35300755, 2022). "MODY is classically defined as a mild diabetes with autosomal dominant inheritance, early age at onset and impaired insulin secretion." (PMID 35592779, 2022). "Induced by decreased insulin secretion or insulin resistance, diabetes is a group of metabolic disorders characterized by increased blood glucose level." (PMID 35957227, 2022). "The patient was diagnosed as fulminant type 1 diabetes mellitus complicated with ketoacidosis induced by anti-PD-1, and was treated with massive fluid rehydration, intravenous infusion of insulin and correction of acid-base electrolyte disorder." (PMID 35784237, 2022). "T1D (proxied by “started insulin within one year of diagnosis of diabetes”) and ankylosing spondylitis were excluded from our analyses because of low heritability, although the direction of association agrees with previous reports." (PMID 35077020, 2022). "Comparing populations with or without DR, patients with DR were significantly more likely to have type 1 diabetes, had a longer course of diabetes, had higher glycated hemoglobin, and mainly were treated with insulin." (PMID 35268409, 2022). "A previous RCT consisting of 216 patients with diabetes on intensive insulin therapy found that the FLASH education program with FGM use improved glycemic control." (PMID 36506077, 2022). "The percentage of correct responses in the Diabetes Knowledge Questionnaire was 46.7%, with the lowest scores related to the knowledge of insulin pumps (36.5%), nutritional principles (37.4%), and insulin therapy and glucagon administration (37.9%)." (PMID 36554455, 2022). "Other abundantly expressed miRNAs in islet cells, such as miR-29a, miR-29b, miR-200 and miR-7, influence the synthesis of insulin by playing a role in the development and proliferation of beta cells and, thus, can be proposed as biomarkers for diabetes." (PMID 36297381, 2022). "Diabetes is a complex metabolic disorder characterized by high glucose levels in the blood (hyperglycaemia) due to insufficient insulin secretion and/or resistance to insulin's action." (PMID 36256488, 2022). "Diabetes mellitus (DM) is a widespread metabolic disorder featuring decreased peripheral insulin sensitivity, impaired insulin secretion from pancreatic β-cells, and overall dysregulation of glucose metabolism." (PMID 35335211, 2022). "Supplemental TMAO to a high-fat diet in mice exacerbated impaired glucose tolerance, suppressed the hepatic insulin signaling pathway and increased adipose tissue inflammation, leading to insulin resistance and diabetes." (PMID 35982495, 2022). "Diabetes mellitus is a disease characterized by persistent hyperglycemia due to impaired response to insulin, or impaired ability to produce insulin." (PMID 35610669, 2022).
diabetes (continued). "Our results were the basis for a discussion about the diagnostic value in the clinical practice of LOX-1 and GAL3 in geriatric patients with diabetes and also provide grounds for inferring the therapeutic benefits of insulin and metformin treatment." (PMID 35742776, 2022). "With insulin therapy, diabetes can be treated effectively, and with the proper control of glycaemia, long-term survival can be achieved." (PMID 35305618, 2022). "Hypoglycemia is a common clinical event in diabetes patients, especially those with intensive glycemic control and using insulin or other hypoglycemic agents." (PMID 35915611, 2022). "The methanol extract of V. radiata seeds also moderated lipid profiles, AST, ALT, and glycated hemoglobin while restoring liver glycogen and insulin levels in diabetic mice, suggesting its potential advantages in reducing some of the consequences of diabetes." (PMID 36337582, 2022). "The treatment of diabetes mellitus in patients with coexisting hyperthyroidism pose a challenge regarding glucose control because hyperthyroidism induces insulin resistance." (PMID 35382047, 2022). "Impaired insulin secretion reduced the sensitivity of target tissues and increased glucose production in the liver are three metabolic abnormalities in diabetes." (PMID 36431053, 2022). "Type 2 diabetes (T2D), the most prevalent type of diabetes in the elderly, is due to insulin resistance in insulin-sensitive tissues such as muscle, liver, and fat with the declining function of pancreatic β-cells in islets of Langerhans." (PMID 35017319, 2022). "Diabetes is a state of hyperglycemia and is characterized by insulin resistance and/or insulin secretion dysfunction." (PMID 35355561, 2022). "Item 14, “I take my diabetes medication like insulin injection as prescribed, observing dosage and time, regularly,” was the most unfitted statement in the DSMS scale as observed by its unsatisfactory MnSq and Zstd." (PMID 36611495, 2022). "Diabetes mellitus is a group of metabolic diseases characterized by hyperglycemia arising from defects in insulin action, secretion, or both." (PMID 35388310, 2022). "Among the patients with diabetes mellitus, 13 were receiving asingle-agent antidiabetic drug, 4 were receiving dual oral antidiabetictherapy, and 1 was receiving insulin therapy." (PMID 35170644, 2022). "Nine patients with PPGL suffered from diabetes, three of them were treated with metformin and one dose of insulin, four patients were treated only with metformin." (PMID 35327387, 2022). "Considering the growing prevalence of diabetes mellitus, an electrochemical sensor for the determination of insulin was proposed for the effective diagnosis of the disease." (PMID 35773298, 2022). "PAHSA administration improves glucose tolerance and insulin sensitivity and reduces inflammation in obesity, diabetes and immune-mediated diseases." (PMID 35676490, 2022). "In contrast, lipoxins have been found to ameliorate insulin sensitivity and possibly inhibit the occurrence and progression of diabetes mellitus." (PMID 35053915, 2022). "One seminal discovery in the treatment of diabetes happened 100 years ago and is the discovery of insulin." (PMID 35454117, 2022). "This “shift” towards a decreased birth weight in patients with diabetes mellitus was also reported in women with type II diabetes randomized to receive metformin or placebo on top of insulin." (PMID 35130922, 2022). "Similar works should be replicated among other populations, in particular among people with diabetes treated with insulin, to improve, for instance, machine learning algorithms of hybrid closed-loop insulin delivery systems." (PMID 34648353, 2022). "This understanding will allow us to assess the effects of insulin replacement and other treatments on impaired bone healing due to diabetes in later studies." (PMID 36060973, 2022).
diabetes (continued). "A mouse knockdown model provided evidence that miR-155 is a positive regulator of insulin sensitivity with potential applications for diabetes treatment." (PMID 36319747, 2022). "Additionally, insulin resistance is a diagnostic sign for obesity-related diabetes mellitus, and it is regarded as the main risk factor for physiological phenomena in which organs such as the liver, skeletal muscle, and adipose tissue are less receptive to insulin." (PMID 35337139, 2022). "Recent research indicates that some people with diabetes engage in the underground exchange of diabetes medications and supplies with online strangers, including insulin donations." (PMID 35436214, 2022). "This was a randomized, open-label, single center study that compared an electronic DOS and nurse phone calls to enhanced standard care (ESC) in hospitalized insulin-requiring patients with type 2 diabetes mellitus." (PMID 35881437, 2022). "Type 2 diabetes mellitus (T2D) is a metabolic disease characterized by reduced insulin sensitivity by target organs or reduced insulin production by pancreatic beta cells." (PMID 36555364, 2022). "Two key features of the pathogenesis of type 2 diabetes mellitus (T2DM) are a decrease in the ability of insulin to fulfil its normal physiological role, insulin resistance, and the inability of pancreatic β cells to adequately secrete insulin." (PMID 36554057, 2022). "Potential risk factors of depression in T2DM patients included women, age ≥ 60 years, low educational level, complications, duration of diabetes ≥ 10 years, insulin use, and living alone." (PMID 35620713, 2022). "Vitamin D also has functions in adipogenesis, glucose-insulin homeostasis, cell growth, non-alcoholic fatty liver disease, diabetes, insulin resistance, and metabolic syndrome." (PMID 36043008, 2022). "On the other hand, a poor glycemic control of maternal diabetes can result to fetal macrosomia due to fetal insulin overproduction as a response to maternal hyperglycemia." (PMID 36440208, 2022). "It is well known that persistence of hyperglycemia because of diabetes results in neuronal damage, inflammatory response, and dysfunction of insulin signaling, as well as cognitive impairment." (PMID 35781592, 2022). "In other models of diabetes and diet-induced obesity, the use of antibodies to block CGRP-α also improved glucose tolerance, insulin sensitivity and resulted in weight loss." (PMID 36175833, 2022). "Diabetes mellitus is a disorder characterized by chronic hyperglycemia in which insulin secretion, insulin action, or both are defective." (PMID 36313351, 2022). "MODY is an early-onset, autosomal dominant presentation of diabetes with a clear heritable component and is thus ripe for studying the genetics of insulin dysregulation and hyperglycemia." (PMID 36383675, 2022). "Leaf and leaf tea is considered a healthy and suitable food in the fight against diabetes, regulating energy metabolism, improving the blood lipid profile, improving insulin sensitivity and lowering blood glucose." (PMID 35050040, 2022). "When access to cheap insulin is limited, those with diabetes who rely on it for survival pay the ultimate price." (PMID 36419111, 2022). "Patients with more than six years of diabetes had significantly higher HbA1c, higher prevalence of hypertension and hyperlipidemia, more diet control, and less insulin use compared to those with fewer than five years of disease." (PMID 36553026, 2022). "Fasting hyperglycemia decreased insulin secretion, and insulin receptor insensitivity are all symptoms of diabetes mellitus, a metabolic condition." (PMID 36305681, 2022). "According to some studies, people living with diabetes have more difficulties adhering to a suitable diet and PA than to insulin medication." (PMID 35793375, 2022). "The range of glucose homeostasis goes from normoglycemia to insulin-treated diabetes with ketoacidosis." (PMID 35052457, 2022).
diabetes (continued). "Regarding the time of ESRD, diabetes, and insulin intake, the groups presented differences only in the meantime with ESRD (4.68 and 6.83 years) for the pre- and post-transplantation groups respectively (p = 0.009)." (PMID 35475809, 2022). "In the case of diabetes, inhibiting this enzyme increases incretin activity and insulin production, leading to improved glucose control." (PMID 36460949, 2022). "Diabetes mellitus (DM) is a metabolic disorder characterized by hyperglycemia due to abnormal insulin secretion." (PMID 35016229, 2022). "Diabetes is a serious metabolic disorder with high rate of prevalence worldwide; the disease has the characteristics of improper secretion of insulin in pancreas that results in high glucose level in blood." (PMID 34996986, 2022). "Their function is also important in improving insulin sensitivity during a high-fat diet in mice; in diabetes, however, it plays a role in its pathogenesis." (PMID 35054822, 2022). "Diabetes occurs due to either decreased insulin production by the pancreas or the body’s inability to use insulin effectively (insulin resistance)." (PMID 36364022, 2022). "Thiazolidinediones, PPAR- γ agonists, are insulin sensitizers used in the management of diabetes and for the treatment of MAFLD." (PMID 36148775, 2022). "Alterations of glucose metabolism and of insulin action in brain of several neurological diseases and Type 2 Diabetes Mellitus." (PMID 35615716, 2022). "As a model of T2D, we used streptozotocin-nicotinamide (Stz-NA) diabetes, which corresponds to T2D: stable moderate hyperglycemia, insulin resistance, and a slight decrease in insulin." (PMID 35457103, 2022). "Benefits of apelin on insulin action would suggest obvious therapeutic potential for diabetes, but some dispute regarding direct effects of apelin on the endocrine pancreas have caused some confusion in this regard." (PMID 35177945, 2022). "Diabetes mellitus is a metabolic disorder characterized by chronic hyperglycemia resulting from defects in insulin secretion, insulin sensitivity, or both." (PMID 35269986, 2022). "Diabetes mellitus, a disease that affects nearly 536.6 million people worldwide, is characterized by the death or dysfunction of insulin-producing beta cells of the pancreas." (PMID 35769082, 2022). "While insulin treatment ameliorated synaptic plasticity and water maze learning deficits in type 1 diabetic rats, efficacy required treatment from onset of diabetes." (PMID 35967127, 2022). "Insulin resistance (IR), designated as the blunted response of insulin target tissues to physiological level of insulin, plays crucial roles in the development and progression of diabetes, nonalcoholic fatty liver disease (NAFLD) and other diseases." (PMID 36555704, 2022). "MDSCs are gradually becoming a favorable candidate for insulin-producing β cells regeneration, thereby treating diabetes." (PMID 35395037, 2022). "A simple mechanistic scheme of the pathogenesis of type 2 diabetes mellitus is hindered by the complex interrelationship between insulin sensitivity and β-cell dysfunction." (PMID 35453469, 2022). "This is perhaps analogous to the benefits in the field of diabetes gained by estimates of insulin resistance and beta‐cell function from insulin and glucose test results using models such as HOMA." (PMID 35938225, 2022). "Diabetes mellitus (DM) is a group of metabolic diseases characterized by a chronic elevation of blood glucose levels above normal limits (hyperglycemia) caused by impaired insulin secretion, insulin resistance, or a combination of the two." (PMID 36294898, 2022). "The independent effects of hyperinsulinemia and hyperlipidemia on the pituitary have been studied, with most groups focusing on the roles of insulin, stress, diabetes and hypoglycemia in activating the hypothalamic-pituitary-adrenal axis." (PMID 35544473, 2022).